IGLV9-49 (immunoglobulin lambda variable 9-49)
Description:
V region of the variable domain of immunoglobulin light chains that participates in the antigen recognition. Immunoglobulins, also known as antibodies, are membrane-bound or secreted glycoproteins produced by B lymphocytes. In the recognition phase of humoral immunity, the membrane-bound immunoglobulins serve as receptors which, upon binding of a specific antigen, trigger the clonal expansion and differentiation of B lymphocytes into immunoglobulins-secreting plasma cells. Secreted immunoglobulins mediate the effector phase of humoral immunity, which results in the elimination of bound antigens. The antigen binding site is formed by the variable domain of one heavy chain, together with that of its associated light chain. Thus, each immunoglobulin has two antigen binding sites with remarkable affinity for a particular antigen. The variable domains are assembled by a process called V-(D)-J rearrangement and can then be subjected to somatic hypermutations which, after exposure to antigen and selection, allow affinity maturation for a particular antigen.
Synonyms: IGLV949; V5-2
Gene: Immunoglobulin variable (V) gene on chromosome 22 (22,343,187 to 22,343,732, forward strand). Ensembl gene ENSG00000223350.
Subcellular location: Secreted; Cell membrane
Gene Ontology:
Biological process: immune response
Cellular component: extracellular region; immunoglobulin complex; plasma membrane
Homologues: Orthologues: macaque IGLV9-49 (93% identical). Paralogues in human: IGLV4-69 (62% identical), IGLV4-60 (59% identical), IGLV4-3 (54% identical), IGLV5-52 (50% identical), IGLV5-37 (49% identical), IGLV5-45 (47% identical), IGLV2-18 (46% identical), IGLV2-8 (46% identical), IGLV1-40 (45% identical), IGLV2-11 (45% identical), IGLV1-50 (44% identical), IGLV1-51 (44% identical), and 81 more.
Diseases named in the same sentence as IGLV9-49 in open-access papers:
IGLV9-49 is named in the same sentence as 1 disease in open-access papers, as found by Europe PMC text mining. Sharing a sentence is not in itself a finding about the gene and the disease. The quoted sentences say what the papers report.
COVID-19 (1 paper, 2025). A disease caused by infection with severe acute respiratory syndrome coronavirus 2. "In particular, two independent studies revealed significant upregulation of IGKV3-7 in asymptomatic COVID-19 individuals and IGLV9-49 in COVID-19 patients respectively, which implies that these two proteins may be involved in acute lung inflammation." (PMID 39358504, 2025).